IKBKE (inhibitor of nuclear factor kappa B kinase subunit epsilon)
Diseases named in the same sentence as IKBKE in open-access papers (continued):
Sharing a sentence is not in itself a finding about the gene and the disease.
infection (51 papers, 2010 to 2026). The state of being infected such as from the introduction of a foreign agent such as serum, vaccine, antigenic substance or organism. "Both IKBKE and NFKBIA encode for inhibitors of NF‐κB and are involved in regulating inflammatory responses to infection." (PMID 35706367, 2022). "A common motif comprised of the genes IKBKE, C1QBP, and EHHADH was found to be directly connected to the HNF4A hub in the infection tolerant state associated with A. baumanii and K. pneumoniae infection." (PMID 35706367, 2022). "In addition, we investigated the effect of knockdown of RNF114 on the expression of IKBKE during SVA infection." (PMID 41319264, 2026). "Furthermore, we investigated the effect of CALCOCO2 knockout on IKBKE expression during SVA infection." (PMID 41319264, 2026). "The expression of IKBKE during SVA infection was further investigated." (PMID 41319264, 2026). "The products of the IKBKE and NFKB1 genes are central to the NF-κB signaling pathway that regulates the expression of many immune-related genes following infection." (PMID 25324841, 2014). "Notably, at the 24-h time point, both IKBKE and NFKB1 were up-regulated in the M. bovis-infected MDM relative to BCG-infected MDM, suggesting that there is increased activation of NF-κB signaling following infection with the virulent mycobacterial strain." (PMID 25324841, 2014).
metabolic disease (13 papers, 2013 to 2025). A congenital disorder (due to inherited enzyme abnormality) or acquired (due to failure of a metabolically important organ) disorder resulting from an abnormal metabolic process. "IKBKE plays a crucial role in cellular immunity, the regulation of NF‐κB‐mediated inflammatory reactions, and the progression of metabolic diseases." (PMID 39287375, 2024). "IKBKE has been described to impact on inflammatory and metabolic diseases as well as on cell proliferation and transformation." (PMID 32855362, 2020). "IKBKE (inhibitor of nuclear factor kappa‐B kinase subunit epsilon), a member of the nonclassical IKK family, plays an important role in the regulation of inflammatory reactions, activation and proliferation of immune cells, and metabolic diseases." (PMID 31733040, 2020).
IKBKE also shares sentences with these, for which no sentence is quoted: Insulin resistance (14 papers); diabetes (6); Hepatic steatosis (6); aphthous ulcers (5); rheumatoid arthritis (5); triple-negative breast carcinoma (5); cardiovascular disease (4); COVID-19 (4); melanoma (4); allergic rhinitis (3); heart failure (3); lymph node metastasis (3); myocardial infarction (3); non-alcoholic fatty liver disease (3); non-small cell lung carcinoma (3); ulcers (3); acute myeloid leukemia (2); Chlamydia infection (2); diffuse large B-cell lymphoma (2); E. coli infection (2); fibrosis (2); hypertrophy (2); inflammatory bowel disease (2); influenza (2); Listeria monocytogenes infection (2); renal cell carcinoma (2); squamous cell carcinoma (2); type 1 diabetes (2); Yersinia infection (2); abdominal aortic aneurysm (1).
A further 70 diseases each share a sentence with IKBKE in 1 paper.